VCAM1 (vascular cell adhesion molecule 1)
Diseases named in the same sentence as VCAM1 in open-access papers (continued):
Sharing a sentence is not in itself a finding about the gene and the disease.
lung cancer (25 papers, 2016 to 2025). A malignant neoplasm involving the lung. "Their studies revealed a positive correlation between the expression of CAF marker proteins, α-SMA and VCAM-1, which was associated with poor prognosis in lung cancer patients." (PMID 40244052, 2025). "Additionally, the analysis showed a positive correlation between the expression of α-SMA and VCAM-1, which is associated with poor prognosis in lung cancer patients." (PMID 40244052, 2025). "Also, CXCL13/CXCR5 axis contributed to cell motility in lung cancer cells, which was caused by VCAM‐1 expression." (PMID 34427969, 2021). "Interestingly, sustained high expression of VCAM1 in fibroblasts is associated with elevated collagen production, as well as promotion of migratory and proliferative behaviors of several lung cancer cell lines." (PMID 40474967, 2025). "VCAM-1 enhances the growth and invasion of lung cancer cells through the AKT and MAPK signaling pathways." (PMID 40244052, 2025). "VCAM-1 expression is also upregulated on the endothelium of rejected transplanted organs, and in breast cancer, lung cancer, and colorectal cancer." (PMID 39769411, 2024). "COL1A1, ACTA2, and alpha-SMA are relatively grouped in lung tissues, and PDGFRA, VCAM1 are expressed in both lung tissues and lung cancer cell lines, showing less specificity." (PMID 39034310, 2024). "Meanwhile, they also indicated that PLCβ, PKCα and c-Src signaling pathways also participated in CXCL13-promoted cell migration and VCAM-1 expression in lung cancer cells." (PMID 37393391, 2023). "Here, we also investigated the correlation between CXCL13 and VCAM‐1 in tissues of lung cancer patients." (PMID 34427969, 2021). "As previous study, the indication of VCAM‐1 is a critical component requiring for lung cancer invasion and further metastasis." (PMID 34427969, 2021). "Our evidence showed that CXCL13 obviously promoted migration of lung cancer cells, and this effect was mediated by vascular cell adhesion molecule‐1 (VCAM‐1) expression." (PMID 34427969, 2021). "Our finding here supposes that CXCL13/CXCR5 axis is a major regulator of VCAM‐1 up‐regulation in lung cancer." (PMID 34427969, 2021). "Meanwhile, CXCR5 neutralized antibody also dose‐dependently reversed cell migration and VCAM‐1 expression in CXCL13‐treated lung cancer cells." (PMID 34427969, 2021). "Conclusively, these results identify the crucial role of CXCR5 receptor in regulating cell migration and VCAM‐1 expression, which caused by CXCL13 incubation in lung cancer cells." (PMID 34427969, 2021). "VCAM‐1 expression correlates with glioblastoma grade, as well as with poor survival in lung cancer 9 and epithelial ovarian cancer." (PMID 34427969, 2021). "In conclusion, our present study suggests that CXCL13/CXCR5 axis is up‐regulated in lung cancer cells, which promotes VCAM‐1 expression and further cell migration." (PMID 34427969, 2021). "Here, we found that VCAM‐1, a cell adhesion molecule associated with metastasis, which was up‐regulated in response to CXCL13 in lung cancer cells." (PMID 34427969, 2021). "The results indicated that pre‐treatment with PLCβ, PKCα and c‐Src inhibitors (U73122, GF109203X and PP2) reversed CXCL13‐promoted cell migration and VCAM‐1 in lung cancer cells." (PMID 34427969, 2021). "In lung cancer, the soluble fraction of VCAM-1 predicted relapse and lower OS, whereas high POSTN expression was associated with shorter PFS in ovarian cancer patients." (PMID 33553157, 2020). "Alternatively, CAF-secreted vascular cell adhesion protein (VCAM)-1 has been shown to stimulate lung cancer cells migration and invasion." (PMID 33553157, 2020). "Downregulation of VCAM-1 is correlated with suppressed lung cancer cell growth, while VCAM-1 knockdown reduces A549 cells’ ability to migrate." (PMID 33262947, 2020). "In this study, using the siRNA-mediated knockdown of VCAM-1, we identified VCAM-1 as a key molecule regulating the invasion of A549 lung cancer cells." (PMID 29614819, 2018).
lung cancer (continued). "In a previous study, we reported that VCAM-1 is highly overexpressed in lung cancer tissues, and that high VCAM-1 expression is closely associated with the poor survival of patients with lung cancer." (PMID 29614819, 2018). "The antibody isolated using this strategy, VCAM-1-D6 huMab, efficiently inhibited VCAM-1-mediated lung cancer cell migration into Matrigel." (PMID 28272300, 2017). "Third, siRNA-mediated knockdown of VCAM-1 in hTNFα-treated A549 human lung cancer cells greatly reduced cell migration into Matrigel, suggesting VCAM-1 is critical for this process." (PMID 28272300, 2017). "In this study, we found that VCAM-1 was highly overexpressed in lung cancer tissue compared with that of normal lung tissue, and high VCAM-1 expression correlated with poor survival in lung cancer patients." (PMID 28272300, 2017). "VCAM-1 expression was higher in lung cancer (n = 9) compared with that in normal lung (n = 10) tissue." (PMID 28272300, 2017). "To investigate VCAM-1 expression in normal lung and lung cancer patient tissue, we performed immunohistochemistry with a commercially available anti-VCAM-1 antibody." (PMID 28272300, 2017). "Prior to performing functional assays, we verified VCAM-1 expression in the human lung cancer cell lines A549 and NCI-H1299 that were cultured in the absence or presence of hTNFα." (PMID 28272300, 2017). "In the present study, we showed that VCAM-1 expression is increased in lung cancer tissue compared with that of normal lung tissue, and that high VCAM-1 expression is associated with reduced survival of lung cancer patients." (PMID 28272300, 2017). "Second, high VCAM-1 expression correlated with poor survival of lung cancer patients, implying that VCAM-1 has a key role in lung cancer progression." (PMID 28272300, 2017). "To elucidate the relationship between VCAM-1 expression and survival of lung cancer patients, we performed bioinformatics-based survival analysis." (PMID 28272300, 2017). "First, compared with normal lungs, VCAM-1 was highly overexpressed at the mRNA and protein level in lung cancer tissue." (PMID 28272300, 2017). "To examine the role of VCAM-1 in lung cancer cell invasion, we performed siRNA-mediated knockdown of VCAM-1 in the human lung cancer cell line A549, which was cultured in the presence of hTNFα to induce VCAM-1." (PMID 28272300, 2017). "Taken together, these expression data suggest that increased levels of VCAM-1 play a role in lung cancer." (PMID 28272300, 2017). "VCAM-1-D6 huMab binds to VCAM-1 and blocks the invasion of VCAM-1-expressing human lung cancer cells." (PMID 28272300, 2017). "In this study, we generated a human antibody to VCAM-1-D6, which is the functionally critical domain for VCAM-1-mediated lung cancer cell migration into Matrigel." (PMID 28272300, 2017). "VCAM-1 expression was significantly increased in lung cancer tissue (n = 226) compared with that in normal lung tissue (n = 20) (p = 0.00015)." (PMID 28272300, 2017). "Furthermore, a VCAM-1 neutralizing antibody prevented the adhesion of the lung cancer cells to cultured brain EC." (PMID 37173970, 2023). "VCAM‐1 expression was also found to be up‐regulated in lung cancers." (PMID 34427969, 2021). "Finally, CXCL13 stimulated NF‐κB transcription factor in lung cancer cells, contributing to VCAM‐1 expression in translational level." (PMID 34427969, 2021). "Finally, we manipulated online gene expression profiling tool GEPIA 27 to assess the correlation between CXCL13 and VCAM‐1 in lung cancer tissues." (PMID 34427969, 2021). "Furthermore, inhibiting VCAM-1, a common product of CAFs, reduced the proliferation and invasion of lung cancer cells, implying that VCAM-1 can be further explored as a potential therapeutic target." (PMID 33808627, 2021). "Finally, PLCβ, PKCα and c‐Src signalling pathways were involved in CXCL13‐promoted cell migration and VCAM‐1 expression in lung cancer cells." (PMID 34427969, 2021).
lung cancer (continued). "We also test the candidate components which are activated after CXCL13 treatment and found that phospholipase C‐β (PLCβ), protein kinase C‐α (PKCα) and c‐Src signalling pathways were involved in CXCL13‐promoted cell migration and VCAM‐1 expression in lung cancer cells." (PMID 34427969, 2021). "Although little is known about the role of Notch signaling in the regulation of VCAM1 expression in macrophages, lung endothelial cells express high levels of VCAM1, and increased numbers of TAMs have been observed in lung cancer tissue compared to that in control." (PMID 29686671, 2018). "Based on our data, we propose a mode of action whereby, under stressful conditions within the tumor microenvironment and in response to certain extracellular stimuli, VCAM-1 expression is abruptly increased on the surface of lung cancer cells to promote lung cancer cell invasion." (PMID 28272300, 2017). "Here, we demonstrated a more effective strategy to develop a functional antibody by first identifying VCAM-1-D6 as a key domain regulating VCAM-1-mediated lung cancer cell migration into Matrigel and subsequently isolating a VCAM-1-D6-specific antibody from a human synthetic antibody library." (PMID 28272300, 2017). "To further examine VCAM-1 expression in normal lung and lung cancer patient tissue, we analyzed lung cancer patient gene expression profiling data (GSE31210) obtained from the National Cancer for Biotechnology Information (NCBI) Gene Expression Omnibus (GEO) database." (PMID 28272300, 2017). "However, we cannot exclude the possibility that other cell types also express VCAM-1 in lung cancer tissue." (PMID 28272300, 2017). "Collectively, these results suggest that VCAM-1 regulates lung cancer cell invasion." (PMID 28272300, 2017). "Furthermore, the antibody-based targeting of VCAM-1-D6 is an effective strategy for inhibiting the invasion of VCAM-1-expressing lung cancer cells." (PMID 28272300, 2017). "In the present study, we propose, for the first time, that the VCAM-1-D6 domain may be a key domain for regulating VCAM-1-mediated lung cancer cell invasion." (PMID 28272300, 2017). "In addition, VCAM1 secreted from CAFs enhanced the growth and invasion of lung cancer cells." (PMID 39451241, 2024). "Our results demonstrated that metformin drug resistance increases the expression of proinflammatory and invasive genes, including BMP5, CXCL3, VCAM1, and POSTN, in A549 lung cancer cells." (PMID 37239373, 2023). "In general, blocking vascular cell adhesion molecule-1 (VCAM-1) by siRNA138 and inhibiting IL-22 with an anti-IL-22 antibody, CAF-CM-promoted proliferation was attenuated via factors downstream of PI3K/AKT signaling cascade in the same type of lung cancer." (PMID 34108441, 2021). "Finally, by developing of a VCAM-1 blocking monoclonal antibody specific to VCAM-1-D6, we found that the antibody specifically inhibited the lung cancer cell migration into Matrigel." (PMID 28272300, 2017). "Although the roles of VCAM-1 have been reported in several types of cancer, the roles of VCAM-1 in lung cancer have not yet been elucidated." (PMID 28272300, 2017). "On the other hand, domain 6 of VCAM-1 appears to be a key target for TNFα-induced angiogenesis, and the antibody blockade of domain 6 impairs leukocyte transmigration but not adhesion, as well as lung cancer cell migration." (PMID 39769411, 2024). "In a lung cancer model, the enhancement of brain metastasis by inflammatory conditions was shown to involve VCAM-1 and ICAM-1 on brain endothelium, but inflammation did not enhance lung cancer cell adhesion to and extravasation from brain vessels or brain metastasis in icam-1 deficient mice." (PMID 37173970, 2023). "However, the role of VCAM-1 and its target domain for antibody therapy in lung cancer cell invasion have not yet been clearly identified." (PMID 28272300, 2017). "However, the relevance and role of VCAM-1 in lung cancer have not been clearly elucidated." (PMID 28272300, 2017).
lupus (23 papers, 2012 to 2024). "The results of the GSEA show that pathways associated with VCAM1 include interactions with the extracellular matrix (ECM), systemic lupus erythematosus, interactions with cytokines and cytokine receptors, focal adhesion, and signaling pathways for chemokines." (PMID 39319258, 2024). "In the current study, the protein level of Vcam1 was significantly higher in the aortas from lupus mice compared to healthy mice." (PMID 39337408, 2024). "Conversely, the aortas from spermidine-treated mice had significantly lower Vcam1 expression compared to aortas from lupus control mice." (PMID 39337408, 2024). "Lupus mice had higher protein levels of Vcam1 in aorta compared with MpJ healthy control mice, suggesting the high inflammatory responses in the vessels of lupus mice." (PMID 39234308, 2024). "The rapamycin-treated mice had significantly lower Vcam1 expressed in vessels compared to untreated lupus mice." (PMID 39234308, 2024). "Our study confirmed the increase in Vcam1 in the aorta of lupus mice, which was reduced by spermidine treatment." (PMID 39337408, 2024). "The protein level of Vcam1 from the thoracic aorta was significantly higher in the lupus-prone mice (lpr_Control, 6.55 ± 1.88 a.u., p = 0.003) when compared to the healthy control mice (MpJ_Control) (1.00 ± 0.11 a.u.)." (PMID 39337408, 2024). "The inflammatory marker, vascular cell adhesion protein 1 (Vcam 1), was elevated in aorta from lupus mice compared with healthy mice (p = 0.001), and significantly reduced with Rapamycin treatment (p = 0.0021)." (PMID 39234308, 2024). "The aim was to study urinary angiostatin, CXC chemokine ligand 4 (CXCL4) and vascular cell adhesion molecule-1 (VCAM-1) as biomarkers of renal disease in systemic lupus erythematosus (SLE)." (PMID 29325582, 2018). "This fits with lupus mouse model studies which show that although local VCAM-1 expression is elevated in lupus-affected organs, ICAM-1 is more critical for transendothelial migration of leukocytes into inflamed tissues." (PMID 26746423, 2016). "The aim of the current study was to compare levels of vascular cell adhesion molecule-1 (VCAM-1) and E-selectin in lupus patients and controls and to investigate their association with clinical phenotype, disease activity and damage." (PMID 24647443, 2014). "The aim of this study was to compare levels of VCAM-1 and E-selectin in a large cohort of lupus patients and a control population." (PMID 24647443, 2014). "E-selectin may act as a marker of cardiovascular risk in SLE, whilst VCAM-1 may have a role as a non-invasive biomarker for lupus nephritis activity." (PMID 24647443, 2014). "We compared levels of serum VCAM-1 and E-selectin in 178 female lupus patients and 69 age-and sex-matched controls." (PMID 24647443, 2014). "Changes in circulating Vcam1 are highly correlated with disease activity and might provide insight into lupus and CVD progression." (PMID 39337408, 2024). "VCAM1 was predominantly involved in chemokine signaling pathway, cytokine-cytokine receptor interaction, leishmania infection, natural killer cell-mediated cytotoxicity, primary immunodeficiency, systemic lupus erythematosus." (PMID 37266443, 2023). "Besides, it is also reported that JKAP limits T cells overproducing ICAM‐1 and VCAM‐1 in the kidney of systemic lupus erythematosus patients." (PMID 35274367, 2022). "The most notable findings were at the DNASE1L3 locus, previously associated with systemic lupus erythematosus, and VCAM1, a locus not previously associated with human disease." (PMID 25332064, 2014). "In murine lupus, VCAM-1 has been shown to be hyperexpressed in the endothelium, in the glomeruli and in the tubules of MRL.lpr mice, as well as on myeloid cells in mice bearing particular lupus susceptibility loci." (PMID 22788914, 2012). "Studies have shown that Vcam1 levels are elevated in serum, urine and kidneys of SLE patients and patients with active lupus nephritis." (PMID 39234308, 2024).
lupus (continued). "Urinary angiostatin, CXCL4 and VCAM-1 are potential biomarkers for SLE, in particular lupus nephritis." (PMID 29325582, 2018). "Our study measured protein Vcam1 from the aorta of lupus and healthy mice to expand the results from the previous literature that determined the increased level of Vcam1 in heart, brain, kidney, and lung of SLE mice." (PMID 39234308, 2024). "Increased VCAM-1 expression is observed in the kidney of lupus-prone mice with active disease when compared to non-autoimmune mice, suggesting a role in mediating leukocyte infiltration in the inflamed kidney parenchyma." (PMID 37854589, 2023). "Correlation between serum VCAM-1 level and coronary calcification/subclinical atherosclerosis has also been reported, irrespective of whether the patient had lupus." (PMID 37854589, 2023). "Soluble VCAM-1 (sVCAM-1) is the most abundant of the circulating CAM, and shows the greatest variation in serum level across a number of inflammatory diseases, with the highest levels observed in active systemic lupus erythematosus (SLE), renal allograft and septic shock." (PMID 26746423, 2016).